IDH1 (isocitrate dehydrogenase (NADP(+)) 1)
Diseases named in the same sentence as IDH1 in open-access papers (continued):
Sharing a sentence is not in itself a finding about the gene and the disease.
tumor (continued). "Among the clinical and histological parameters, age (>55 years), WHO tumor grade (GBM), Karnofsky performance score (KPS) (below 90 %), and absence of IDH1 or IDH1 mutation status were significant negative predictors of OS." (PMID 27796446, 2016). "They showed that levels of several amino acids and TCA cycle intermediates were reduced in mutant IDH1 cells relative to wild-type and similar results were obtained in a subsequent study of patient-derived mutant IDH1 tumor samples." (PMID 27144334, 2016). "Although our analysis suggests an evolutionary link between mesenchymal GBMs and IDH1/2 wt LGGs, it does not preclude other tumor evolutionary pathways leading to the formation of mesenchymal GBMs." (PMID 27923049, 2016). "Our work presents an example of one mechanism, outside of the sustained effects imparted by hypermethylation, whereby expression of the mutant IDH1 can compromise HIF1α induction in response to hypoxia to modify the ECM and alter tissue mechanics and tumour aggression." (PMID 27820599, 2016). "Multivariate analysis on IDH1-R132H expression, differentiation, tumor stage, and CEA level revealed that IDH1-R132H expression (HR, 0.156, P<0.001), differentiation (HR, 2.653, P=0.013), and tumor stage (HR, 1.551, P=0.022) are independent prognostic risk factors." (PMID 27655638, 2016). "Serum albumin levels did not vary significantly with sex, age, tumor size, degree of resection, MGMT promoter methylation and IDH1-R132H mutation status." (PMID 25880463, 2015). "In contrast, in patients with IDH1-R132H negative tumours, only edema ≥ 1 cm beyond the tumour margin and mitoses < 5 / mm2 were positively associated with an increased risk of death." (PMID 25849605, 2015). "Among the genes that are mutated between 5 to 20% in TCGA GBM tumor samples, we found mutations in NF1, SPTA1, TCHH and ATRX genes, although, the other genes like PIK3R1, PIK3CA, RB1, IDH1 and KEL were not mutated in any cell line." (PMID 26496030, 2015). "Although IDH1-R132H positive tumours tended to be larger than IDH1-R132H negative tumours, the difference was not statistically significant (62.2 ± 50.0 cm3 vs. 37.9 ± 29.6; p = NS)." (PMID 25849605, 2015). "At the very least, our results demonstrate that the presence of CE on MRI does not rule out an IDH1-positive tumour." (PMID 25849605, 2015). "Compared to IDH1-R132H negative tumours, IDH1-R132H positive tumours demonstrated a significantly lower Ki67 LI (0.14 ± 0.10 vs. 0.24 ± 0.15; p = 0.034)." (PMID 25849605, 2015). "Relative to IDH1-R132H negative tumours, IDH1-R132H positive tumours demonstrated a significantly higher minimum ADC (1.115 x 10-3 ± 0.326 x 103 mm2/sec vs. 0.838 x 10-3 ± 0.266 x 103 mm2/sec; p = 0.016)." (PMID 25849605, 2015). "Mutant specific (R132H) isocitrate dehydrogenase-1 (IDH1) immunohistochemistry was negative, and the tumor lacked detectable 1p or 19q deletions by fluorescent in situ hybridization (FISH)." (PMID 25755903, 2015). "Anaplastic oligoastrocytomas accounted for 33% and 15% of the tumours in the IDH1-positive and IDH1-negative groups, respectively." (PMID 25849605, 2015). "Among the 6 AOA tumours 5/6 had IDH1 mutations, and all 6 were judged to show methylation of MGMT Considering only tumours where we had results from both MGMT and IDH1/2 assays, among the AA 34/39 were judged to have methylation of MGMT and 31 of these 34 (91%) had IDH1 mutations." (PMID 24952577, 2014). "In our series too, the majority of IDH1 mutant, arcade-negative tumours were non-enhancing, unlike IDH1 wild type, arcade-containing tumours." (PMID 23451042, 2013). "Tumor DNA was analyzed for alterations in selected genetic loci (1p36, 9p22, 10q23–24, 17p13, 19q13, 22q12), isocitrate dehydrogenase 1 (IDH1), isocitrate dehydrogenase 2 (IDH2) and the CpG island methylation status of critical tumor-related genes (MGMT, P16, DAPK, PTEN, RASSF1A, Rb1)." (PMID 23826216, 2013).
tumor (continued). "Although the impact of targeting the mutant enzyme with an IDH1 specific inhibitor has been evaluated, the effect was modest and did not lead to tumor regression." (PMID 24077826, 2013). "By contrast, arcade-like structures were restricted to IDH1 wild-type tumours (0/8 IDH1 mutant vs 48/262, 18%), which were also never observed in patients under the age of 40 years at diagnosis (0/12 vs 48/260, 18%, p = 0.09, Fishers exact test)." (PMID 23451042, 2013). "In the second tumor pair (OII, ID21818 and OIII, ID22328) the molecular alterations, i.e. LOH1p/19q and IDH1- mutation observed in the primary lesion (ID21818) were no longer detectable in the recurrence (ID22328)." (PMID 22844452, 2012). "As most, if not all, tumor suppressor genes are inactivated by epigenetic silencing, in a wide variety of tumors, we asked if IDH1 or IDH2 carry the epigenetic signature of a tumor suppressor by assessing cytosine methylation at their promoters." (PMID 23267435, 2012). "We hypothesized that if IDH1 and IDH2 functioned as tumor suppressor genes, then some tumors may exhibit dense hypermethylation of the CpG island associated with their promoter region." (PMID 23267435, 2012). "The mouse model used in this study was IDH1 and IDH2 wild-type, thus our findings revealed that combining gemcitabine with radiation was efficacious in reducing tumor burden and prolonging median survival when compared to radiation or gemcitabine alone in this class of GBM." (PMID 22536446, 2012). "Taken together, these findings suggest that at least in some circumstances IDH1 and/or IDH2 may function as a typical tumor suppressor gene." (PMID 23267435, 2012). "In our study, the expression of IDH1 does not correlate some other clinical features such as age, localization of primary tumor and histological type." (PMID 20459648, 2010). "The tumor was negative for IDH1 p.R132H mutant protein expression with retained ATRX expression." (PMID 41736408, 2026). "However, radiographic tumor shrinkage was rare, with an ORR of about 2%; the disease control rate was driven predominantly by stable disease, indicating that IDH1 inhibition in this setting mainly achieves disease stabilization rather than radiological remission." (PMID 41535645, 2026). "Although the difference lacked statistical significance, this implies that IDH1 expression may influence tumor angiogenesis." (PMID 40944023, 2025). "This may reflect either relaxed positive selection for the mutant IDH1 locus, or negative selection for the hypermethylation phenotype later in tumor evolution." (PMID 41299743, 2025). "However, in tumor cells, reductive carboxylation of AKG may occur through IDH2 or its cytosolic isoform IDH1." (PMID 40863152, 2025). "Additionally, research has shown that in xenograft tumor models, where wild-type IDH1-expressing human GBM cells are transplanted into nude mice, reducing TNC expression levels significantly decreases ECM stiffness in tumor tissues and prolongs survival in mice with tumors." (PMID 40046232, 2025). "Based on these mechanistic insights and strong correlation of mIDH1 with the non-T cell-inflamed phenotype across tumor types, we hypothesized that IDH1 inhibition combined with ICI may be an effective treatment strategy for patients with mIDH1 tumors." (PMID 41138165, 2025). "APOLLO distinguished tumor from non-tumor tissue and IDH1 wildtype from IDH1 mutant." (PMID 40949165, 2025). "IDH1/2 was wild-type in all cases, regardless of the tumor location." (PMID 39061104, 2024). "A previous study reported that the negative correlation between mRNAsi and tumor pathology was restricted to LGG, which may be due to the reduced cell differentiation caused by IDH1 mutation." (PMID 38229597, 2024).
tumor (continued). "This implies that ATRX losses, which lead to an alternative lengthening of telomeres, may not be sufficient on their own to drive tumor formation but may complement mutant IDH1 expression, suggesting their potential functional synergism." (PMID 39160568, 2024). "Interestingly, a rare IDH1 R132C was identified in CSF ctDNA, but not in the corresponding tumor sample." (PMID 37822669, 2023). "However, after treatment, the tumor weight of control mice did not change significantly, while it was decreased in CT26 tumors with an IDH1 mutation." (PMID 37741882, 2023). "We found that the tumors with alterations in FGFR2 and IDH1/2 had a “non-inflamed” tumor phenotype." (PMID 37190307, 2023). "Our finding of similar MRI appearances in tumours with both IDH1-R132H and non-canonical IDH mutations demonstrates the ability of radiogenomics to provide additional insights into tumour biology, showing that a variety of related genetic mutations result in a common imaging phenotype." (PMID 37316586, 2023). "In addition, unique gene mutations of CCA that should induce DNA methylation events, such as those in IDH1/2, are exclusively observed in tumors showing a non-inflamed tumor phenotype." (PMID 37190307, 2023). "Additionally, neither immune nor tumor cells with wild-type or muted IDH-1 displayed statistical differences in TMIGD2 expression (p= 0.0685; 0.1592)." (PMID 37261362, 2023). "Age and tumor volume were inversely correlated with MMSE concentration component (r = −4.78, p < .01), and with MMSE concentration (r = −.401, p < .01), TMTB (r = −.328, p < .01), and COWAT phonemic scores (r = −.599, p < .01), respectively, but only for the IDH1 wild-type group." (PMID 36970174, 2023). "In addition, unique gene mutations of CCA that should induce DNA methylation events, like those in IDH1/2, are exclusively observed in CCAs carrying a non-inflamed tumor phenotype." (PMID 37190307, 2023). "Finally, 83% (15/18) of the plasma ctDNA-negative samples obtained from the six patients with IDH1-mutant tumors (NGS) occurred in patients with treated disease or without evidence of tumor progression." (PMID 35740557, 2022). "Therefore, our transcriptomic profiling of pHGA in cerebellum (grade III, IDH1/2 and H3F3A wild-type) and cerebrum (grade IV, IDH1/2 and H3F3A wild-type) may greatly contribute to the understanding of these tumor subtypes." (PMID 36293551, 2022). "Likewise, in patient #34, the discontinuation sample at +169 days showed the presence of one CTC that did not contain that tumor’s dominant PIK3CA mutation, but instead harbored a hotspot IDH1 mutation (#34, Discontinuation, CTC#: E6)." (PMID 34866317, 2022). "Together, these data revealed common features of GBM, including gain of chr.7 and loss of chr.10, lacking IDH1/2 mutations, high frequency of TERT promoter mutation, loss of critical tumor suppressors (e.g., PTEN and CDKN2A/CDKN2B), high frequency of PDGFA and EGFR amplification." (PMID 34987659, 2022). "The amount of carnitine derivatives, including propionylcarnitine, is lower in IDH1 and IDH2 mutants, which can contribute to increased fatty acid synthesis, decreased oxidation of certain fatty acids, and accelerated proliferation of cancer cells and tumor growth." (PMID 35053475, 2022). "There was evidence that IDH1 mutant tumors were non-contrast enhancing tumor (nCET) positive." (PMID 35330402, 2022). "No recurrent initiating genetic drivers have been reported in the remaining 30% of IDH1/2 wild type (IDHwt) cases, although these tumours have been reported to exhibit different methylation profiles compared to IDH1 and IDH2-mutant tumours, hereafter referred to as IDH1 and IDH2 tumours." (PMID 36042521, 2022).
tumor (continued). "Furthermore, multivariate analysis showed that tumor recurrence (HR = 2.375 and P=0.028), WHO grade (HR = 2.679 and P=0.031), IDH1 wild-type (HR = 6.473 and P < 0.001), and high VASH1 expression (HR = 4.996 and P < 0.002) were independent risk factors for LGG patients." (PMID 36504559, 2022). "Expression level of endogenous IDH1 protein was not altered as compared to control non-transduced iNS tet cells and was reminiscent of that in IDH1-mutant neurospheres generated from xenograft-forming tumor." (PMID 32946483, 2020). "However, NGS analyses of two subareas containing no tumor cells also show c.359G>A change indicating a false detection of IDH1 c.395G>A." (PMID 32333643, 2020). "However, the number of non-enhancing tumours was limited (n = 13), especially the IDH1-wildtype tumours (n = 3) and the result was not conclusive." (PMID 32382870, 2020). "Therefore, noninvasive and preoperative prediction of the MGMT genotype in patients with IDH1-wildtype GBM by using computational model is possible with the help of wavelet transform features or nonenhanced part of the tumor core (NET)-hit features." (PMID 32942564, 2020). "Three tumor samples with IDH1 wild type showed negative correlations." (PMID 32604718, 2020). "The NHAIDH1mut model, which was generated from immortalized normal human astrocytes 39, 58, provides a robust platform to investigate the role and consequences of mutant IDH1 but is unlikely to reproduce the full complexity of a mutant IDH1 tumor in the patient." (PMID 32754276, 2020). "A universal feature of IDH1/2 mutant cancers is the CpG island methylator phenotype resulting in global DNA hypermethylation, due to the overproduction of 2-HG regardless of tumor type." (PMID 31727977, 2019). "Notably, TMZ + Bev suppressed tumor growth only in the IDH1-mutant U87 xenograft, whereas neither TMZ nor Bev monotherapy inhibited tumor growth in either cell type and IDH1-wiltype tumors did not respond to Bev + TMZ." (PMID 31443404, 2019). "Among the proteins of interest (NPM1, FLT3, DNMT3A, IDH1, IDH2, KIT, and RAS), non-mutation bearing ligands from NPM1 were the most frequent in both patient tumor samples and cell lines, including ligands close to or corresponding to where hotspot mutations occur (EAIQDLWQW and MTDQEAIQDLWQWR)." (PMID 31291378, 2019). "Moreover, the combined expression of H2AFJ and HDAC3 was appeared to be inversely correlated with the time to new tumor event after TMZ therapy in the wild-type IDH1/non-G-CIMP GBM patients." (PMID 31906036, 2019). "This may be related to the location of IDH1-mutant tumors, which mainly occur in the frontal lobe; thus, these patients do not exhibit clinical symptoms until the tumor has grown much larger." (PMID 31275753, 2019). "For example, mutant IDH1 inhibition could efficiently reduce the 2HG levels, but this may not equate with tumor cell death." (PMID 29662077, 2018). "Indeed, this is likely to become increasingly important in hypoxic conditions, such as those observed in the tumor microenvironment, and may explain why oxidative TCA metabolism is increased in IDH1 mutant cells, even when oxygen becomes limiting." (PMID 29562167, 2018). "As both, IDH1 mutation and MGMT expression, can predict outcome of therapy obtained in vitro results cannot directly be translated to the clinical situation of our tumor sample analysis." (PMID 29755294, 2018). "However, it is not clear if the IDH1 mutant ctDNA molecules derived from tumor or nontumor mosaic tissues." (PMID 28834325, 2017). "CNN structures with stronger tumor recognition ability, such as CNN structures based on multiple imaging modalities, could provide more value relevance information and lead to better discrimination of IDH1 statues." (PMID 28710497, 2017).
tumor (continued). "Unless that mutation is too frequent to occur by simple coincidence in that type of tumor, labeling IDH1 R132 or IDH2 R172 mutations as driver ones in a tumor not frequently seen to harbor them and without proving the high content of (D)-2HG in that tumor, should be advised against." (PMID 28785398, 2017). "Another known pathway where tumor cells maximize citrate synthesis, is through the excessive utilization of glutamine and glutamate to produce 2KG, an indirect precursor of citrate through the reductive carboxylation reaction catalyzed by IDH2 within the mitochondria and IDH1 within the cytosol." (PMID 28785398, 2017). "The trunk alterations that existed throughout the course were restricted to IDH1 mutation, 1p/19q-codeletion, and TERT promoter mutation, and mutation of the known candidate tumor suppressor genes CIC and FUBP1 were not consistently observed between primary and recurrent tumors." (PMID 28270234, 2017). "Thus, we propose that IDH1.R132H was probably detected more in the metastatic tissue because none the GBM patients died early due to the primary tumor." (PMID 29038591, 2017). "Tumor cells were positive for IDH1(R132H) and negative for ATRX." (PMID 26817999, 2016). "With respect to mutant IDH1-mediated biology, this result would also suggest that 2-HG-induced changes, such as global DNA hypermethylation, are either potentially reversible or, if not, are insufficient for tumor maintenance." (PMID 26858939, 2016). "Thus, the classification scheme showed prognostic value independent of tumor grade, IDH1/2 status, patient age and therapies (not independent of IDH1 status, age, MGMT promoter methylation and therapies in TCGA GBM samples)." (PMID 27323851, 2016). "The purpose of this study was to determine whether any of the radiological or pathological variables assessed could reliably distinguish IDH1-R132H positive from IDH1-R132H negative tumours in this patient population." (PMID 25849605, 2015). "This discrepancy may be explained by the different methods used to define a tumour as 'non-CE' or by the small number of IDH1-positive tumours in the previous study." (PMID 25849605, 2015). "First, radiological data may be exploited by clinicians to better predict the IDH1 status of the tumour, in particular cases when a tissue diagnosis is not possible." (PMID 25849605, 2015). "IDH1-R132H-positive and -negative anaplastic tumours demonstrate unique features." (PMID 25849605, 2015). "Indeed, 72% of patients with IDH1-R132H positive tumours were younger than 50 years old whereas 68% of patients with IDH1-R132H negative tumours were older than 50 years." (PMID 25849605, 2015). "For example, it was inappropriate to perform a multivariate analysis to identify variables independently associated with death because several groups were characterized by ‘zero’ events (e.g. no patients less than 50 years old and with IDH1-R132H positive tumours died)." (PMID 25849605, 2015). "In contrast, only 3 of 19 IDH1-R132H negative tumours (16%) were located in the frontal lobe." (PMID 25849605, 2015). "Interestingly, this paradox has been brought into even sharper focus by the striking mutational profiles that do exist in very specific 'metabolic’ tumor suppressor genes (that is, FH and SDH) that are inactivated in specific rare cancer syndromes, and in the IDH1 and 2 oncogenes." (PMID 24491179, 2014). "LC-MS and in situ mass spectrometric imaging by LESA-nano ESI-FTICR revealed high levels of the proposed oncometabolite D-2-hydroxyglutarate (D-2HG), the product of enzymatic conversion of α-ketoglutarate (α-KG) by IDH1-R132H, in the tumor but not in surrounding brain parenchyma." (PMID 24252742, 2013).